YAP1 (Yes1 associated transcriptional regulator)
Diseases named in the same sentence as YAP1 in open-access papers (continued):
Sharing a sentence is not in itself a finding about the gene and the disease.
cancer (continued). "Firstly, we utilized univariate Cox proportional hazard regression models to analyze the association between YAP1 expression in pan-cancer and OS or DFS." (PMID 35685435, 2022). "In this study, from a pan-cancer perspective, high expression of YAP1 was associated with upregulation of TGF-β signaling, KRAS signaling, Hedgehog signaling, EMT, and androgen response in most cancer types." (PMID 36479120, 2022). "CircLONP2 is a circular RNA implicated in the development of many cancers, and miR-584-5p and YAP1 have been reported to contribute to the progression of BC." (PMID 35358000, 2022). "The DR-MSCs population resembled cancer initiation cells and were subjected to further analysis of the yes associated protein 1 (YAP1) network." (PMID 35356283, 2022). "Noticeably, TEAD1 knockdown strongly accentuated the proliferation deficiency of siROBO3 treated cancer cells, pointing to sensitization of these cells to further interferences with the YAP1-signaling." (PMID 36057630, 2022). "According to previous literature, YAP1 has a variety of roles in cancer cells, including those associated with CCA." (PMID 35449153, 2022). "MiR-92 targeted Yes-associated protein 1 (YAP1) and their interaction further increased PD-L1 levels in cancer cells, and PD-L1 significantly induced apoptosis and impaired proliferation of T cells, and also prevented the cell killing function of NK cells." (PMID 36185265, 2022). "Intriguingly, the association between miR-205 and YAP1 has been explored in activated cancer-associated fibroblasts (CAFs) of breast tumors." (PMID 35701841, 2022). "YES-associated protein 1 (YAP1) is another key co-transcriptional regulator of AXL in various cancer systems." (PMID 35572601, 2022). "A high YAP1 activity has been associated with proliferation, survival, stemness, invasion, and therapy resistance in various cancers." (PMID 36045416, 2022). "As the core factor of the Hippo pathway, Yes-associated protein (YAP1) acts as an oncogene that is activated in various human cancers." (PMID 35264157, 2022). "Dysregulation of the Hippo signaling pathway has been implicated in multiple pathologies, including cancer, and YAP1 is the major effector of the pathway." (PMID 36479120, 2022). "We found that YAP1 expression was associated with infiltration of cells in both innate and adaptive immune system in pan-cancer." (PMID 36479120, 2022). "A comprehensive molecular characterization of the Hippo signaling pathway across 33,000 sample sets of various cancers showed that high YAP1 expression is associated with poor survival across various cancer types." (PMID 35407556, 2022). "We identified deletion of 18q21.2 and amplification of 11q22.2 as prevailing copy-number alterations in FA HNSCCs, the latter of which was associated with strong overexpression of the cancer-related genes YAP1, BIRC2, BIRC3 (at 11q22.1-2)." (PMID 34997070, 2022). "What’s noteworthy is that existing evidence indicates that KDM3A activates the expression of yes-associated protein 1 (YAP1) in a plethora of human carcinomas." (PMID 36700466, 2022). "The YAP1/Hippo signaling pathway was closely associated with GC progression, and YAP1-induced dysregulation of Hippo pathway contributed to cancer development." (PMID 33975517, 2021). "As a transcriptional cofactor, Yes-associated protein-1 (YAP1) is known to modulate the transcriptional activity of various transcription factors to regulate and maintain cancer stem cell properties and organ size during embryonic development." (PMID 34395416, 2021). "Here, we identified the expression of candidate markers including HMGB1, SOX9, and YAP1, implicated in the cancer development of patients with CCA using genomic datasets from GEO." (PMID 35201494, 2021). "Our findings on the unique function and associated regulatory mechanisms between different YAP1 isoforms should facilitate more efficient and precise therapeutic targeting of this critical pathway for cancer therapy." (PMID 34094936, 2021).
cancer (continued). "In contrast to the temporary activation of YAP1 observed in wound healing, the continuous and persistent activation of YAP1 in adult tissues is associated with cancer and resistance to therapy." (PMID 34685695, 2021). "A total of 482 genes were positively associated with YAP1, and 441 genes were negatively associated with YAP1 across the three types of cancers." (PMID 34257617, 2021). "Yes-associated protein-1 (YAP1) is an important effector of the Hippo pathway and has crosstalk with other cancer signaling pathways." (PMID 34150844, 2021). "The present study managed to investigate this issue and found that ANXA6-exo promoted PTX resistance and cancer progression in BC cells in a Yes-associated protein 1 (YAP1)-dependent manner." (PMID 34676207, 2021). "For instance, the overexpression of yes associated protein 1 (YAP1) that contributes to EMT can transform differentiated cancer cells into CSCs." (PMID 33579377, 2021). "In normal fibroblasts, YAP1 is located in the cytoplasm, while in the activated cancer-associated fibroblasts, it translocates in the nucleus and promotes the expression of genes required for pro-tumorigenic functions." (PMID 34905501, 2021). "Dysregulation of the Hippo signaling pathway is implicated in many types of cancers; for instance, YAP1/TAZ and TEAD are upregulated in a variety of human tumors by mechanisms that include gene amplification and silencing of upstream components of the pathway." (PMID 34206989, 2021). "Less relevant classes were involved in transcription, cell potency, and cancer-associated pathways such as the Hippo/YAP1 and Wnt/β-catenin axes." (PMID 33747361, 2021). "Yes-associated protein 1 (Yap1), a potent oncogene abnormally overexpressed in various cancers, is regulated by the Hh signaling pathway." (PMID 33467481, 2021). "Vestigial Like Family Member 4 can inhibit organ overgrowth and cancer formation caused by YAP1 dysregulation in both human and Drosophila." (PMID 34150758, 2021). "In the present study, we comprehensively analyzed YAP1 expression and its association with prognostic values in pan-cancers via multiplatform such as the Oncomine, GEPIA, UALCAN, and DriverDBv3." (PMID 34257617, 2021). "In this study, we found that YAP1 expression is associated with prognosis in several types of cancer." (PMID 34150844, 2021). "Dysregulation of the pathway is implicated in many types of cancers; for instance, YAP1/TAZ and TEAD are upregulated in a variety of human tumors by mechanisms that include gene amplification and silencing of upstream components of the pathway." (PMID 34206989, 2021). "Yes-associated protein 1 (YAP1), also known as YAP or YAP65, is a transcriptional co-activator and is involved in lots of cancer progression." (PMID 32528231, 2020). "Yes associated protein 1 (YAP1), which is a standout amongst the most essential effectors of the Hippo pathway, assumes a vital part in a few kinds of cancer." (PMID 33240680, 2020). "Yes-associated protein 1 (YAP1) has been reported to be involved in the tumorigenesis and progression of several cancers, thus leading to poor prognosis of patients." (PMID 33123286, 2020). "The Hippo-Yes-associated protein 1 (YAP1) signaling pathway has emerged as a target for the development of new therapeutic interventions in cancers." (PMID 32218280, 2020). "Data on YAP1 and AR expression from 7,971 cancers showed a significant association between AR expression and cytoplasmic and nuclear YAP1 staining." (PMID 32488048, 2020). "Active YAP1 is also recognized as a potent oncogene closely linked to the progression of several cancer types." (PMID 32054505, 2020). "In the eyes of mechanotransduction, fluid shear stress activates YAP1 protein (yes-associated protein 1) which starts a step cascade that promotes cancer cell motility, since it is a potent oncogene present in several cancer types." (PMID 32117980, 2020).
cancer (continued). "High cytoplasmic and nuclear YAP1 were both significantly linked to cancers with TMPRSS2:ERG rearrangement and ERG expression." (PMID 32488048, 2020). "Despite clear evidence for YAP1 in both cancer initiation and progression, few mutations involving YAP1 or other Hippo pathway components have been identified in cancers." (PMID 31913126, 2020). "Both in vitro and in vivo evidence indicates that dysregulation of the Hippo signaling cascade and activation of proto-oncogene YAP1 are linked to many human cancers, including cancers of the skin, lung, colon, breast, kidney, liver, and ovary." (PMID 30840887, 2019). "Liu and colleagues identified circRNA-000425 as a novel inhibitory target of Yes-associated protein 1 (YAP1), an transcriptional coactivator factor that acts as an oncogene associated with cancer malignancy in several cancer types." (PMID 30999909, 2019). "YAP1 has been associated with stemness in cancer cells and its inhibition has been shown to interfere with growth of stem-like cells." (PMID 31100813, 2019). "The first meta-analysis regarding YAP1 was published three years ago, and reported that the positive expression of YAP1 was associated with poorer prognosis in various cancers." (PMID 31613226, 2019). "Activation of YAP1 and its downstream target genes is associated with resistance to DNA-damaging agents, UV, and radiation in different types of cancer." (PMID 31575084, 2019). "To clarify it further, we investigated the association between YAP1 expression and cancer patients’ prognosis in the online database, GEPIA." (PMID 31613226, 2019). "To further investigate the association between YAP1 expression and patients’ prognosis in various cancers, we performed the survival analysis using GEPIA." (PMID 31613226, 2019). "The co-transcription factor yes-associated protein 1 (YAP1) serves as a main downstream effector of the Hippo pathway and its dysregulation increases cancer development and blocks colonic tissue repair." (PMID 31216773, 2019). "Yes‐associated protein 1 (YAP1) is the key effector of the Hippo pathway, which is silenced in most human cancers." (PMID 31145543, 2019). "We showed that the YAP1–NMU correlation promoted cancer metastasis and was associated with poor prognosis in databases and clinical samples." (PMID 31575084, 2019). "The Cancer Genome Atlas data indicated that high YAP1 and NMU expression levels were associated with poor mean and overall survival." (PMID 31575084, 2019). "The association of YAP1 with Kras or PKCι, and its implication in sustaining the survival of cancer cells have been documented in separate studies." (PMID 30214681, 2018). "In normal fibroblasts, YAP1 is located in the cytoplasm, while in activated cancer-associated fibroblasts, it is nuclear and promotes the expression of genes required for pro-tumorigenic functions." (PMID 29909276, 2018). "Yes-associated protein 1 (Yap1), a cornerstone of oncogenic Hippo signalling, is frequently overexpressed in cancer and synergises with Wnt signalling to induce EMT43,44." (PMID 30202034, 2018). "Immunocytochemical data revealed that AZD0530 promotes cytoplasmic YAP1 accumulation and loss of nuclear expression in cancer cells." (PMID 30504771, 2018). "Our data collectively suggest that AZD0530 reverses the LIF-associated cancer invasive phenotype, at least partly, by increasing cytoplasmic YAP1 and suppressing expression of the focal adhesion components p-PXN and p-FAK." (PMID 30504771, 2018). "Together, these data show that the Yap1/NF-κB axis promotes cancer-associated metabolism and that inhibition of this pathway allows expression of muscle markers and muscle-associated metabolism." (PMID 30382078, 2018). "Here we demonstrated a correlation between EGFR mutation and YAP1 expression using both human tissues and cancer cell lines." (PMID 29163769, 2017).
cancer (continued). "Yes-associated protein 1 (YAP1) stimulates cell proliferation, epithelial-to-mesenchymal transition, invasion and metastasis in several cancers." (PMID 28036290, 2017). "An increased expression of Yes-associated protein (YAP1) has been shown to promote tumorigenesis in many cancer types including colon." (PMID 28241877, 2017). "YAP1 is overexpressed in many cancers and YAP1 activity is associated with enhanced stem cell survival in epidermis and other tissues." (PMID 29088716, 2017). "Overexpression of YAP1 has been implicated in promoting resistance to chemo-, radiation and targeted therapy in various cancers." (PMID 29228705, 2017). "Overexpression of the oncogene yes-associated-protein-1 (YAP1) is associated with increased cell proliferation in human cancers." (PMID 27705928, 2016). "Similar to our findings, a meta-analysis study confirmed that YAP1 overexpression was associated with lower overall survival and lower disease-free survival in other cancers." (PMID 27705928, 2016). "Yes-associated protein 1 (YAP1) plays an important role in the development of carcinomas such as breast, colorectal, and gastric (GC) cancers, but the role of YAP1 in GC has not been investigated comprehensively." (PMID 27835600, 2016). "Elevated YAP1 activity due to mutations in Hippo pathway components or YAP1 amplification is observed in several types of human cancers." (PMID 26295846, 2015). "Loss of Hippo signaling by mutations or down-regulation of core pathway components is associated with cancer development, while YAP1 is reported as a potent oncogene that can promote tumorigenesis in a wide range of tissues." (PMID 26295846, 2015). "In the subgroups according to staining location, different ethinicities, cancer systems and the study quality, our results indicated that the positive YAP1 expression was statistically significantly associated with the poor prognostic outcomes." (PMID 26263504, 2015). "YAP1 has a potent growth promoting activity and the YAP1/Hippo pathway has been tightly linked to cancer." (PMID 26295846, 2015). "The YAP1/Hippo signaling pathway is a key regulator of organ size and tissue homeostasis, and its dysregulation is linked to cancer development." (PMID 26295846, 2015). "Yes-associated protein (YAP-1) is the downstream effector of the Hippo signaling pathway, which is frequently overexpressed in many types of cancers." (PMID 26317542, 2015). "Yes-associated protein 1 (YAP1), the key transcription factor of the mammalian Hippo pathway, has been reported to be an oncogenic factor for many cancers." (PMID 24621512, 2014). "The prevailing view in the cancer field is that Hippo signaling pathway functions as a tumor suppressor pathway by blocking the oncogenic potential of the pathway effectors Yes1 associated transcriptional regulator (YAP)/transcriptional coactivator with PDZ-binding motif (TAZ)." (PMID 38979373, 2025). "Snail family transcriptional repressor 2 (Snail2) and yes-associated protein 1 (YAP1) are known oncogenes that are up-regulated in cancer, circRNAPCNX serves as a sponge for miR-506 and inhibits the anti-cancer activity of miR-506 via the circRNAPCNX-miR-506-Snail2/YAP axis in HCC." (PMID 40248198, 2025). "Moreover, a meta-analysis that included various cancers showed that YAP1 positivity is significantly associated with poor overall survival (HR = 1.83, 95% CI 1.47–2.28) and disease-free survival (HR = 2.11, 95% CI 1.41–3.18)." (PMID 41256331, 2025). "YAP1 is implicated as a driver of resistance in KRAS-mutant cancers." (PMID 41193428, 2025). "It would be of interest to investigate whether there is an association between YAP1 signaling in males that contributes to male predisposition to cancer." (PMID 40741215, 2025). "Interestingly, it was observed that EBV-positive NPC cells would contribute to treatment resistance by inducing cancer-associated fibroblast-mediated immunosuppression through YAP1/FAPα signaling." (PMID 40160826, 2025).
cancer (continued). "Moreover, miR-214-3p has been related to the identification of cancer stem cells (CSCs) by targeting Yes-associated protein 1 (YAP1), suggesting a potential therapeutic strategy for squamous lung cancer." (PMID 40191724, 2025). "Furthermore, yes-associated protein 1 (YAP1) overexpression has been shown to contribute to the development of enzalutamide resistance by inducing the acquisition of cancer stemness and activating lipid metabolism in PCa cells." (PMID 39781521, 2025). "The prevailing view in the cancer field is that Hippo (Hpo) signaling pathway functions as a tumor suppressor pathway by blocking the oncogenic potential of the pathway effectors Yes1-associated transcriptional regulator (YAP)/transcriptional coactivator with PDZ-binding motif." (PMID 40120683, 2025). "YAP1 is a transcriptional co-activator in the Hippo pathway, which controls cell proliferation, apoptosis, and organ size, and is strongly linked to the development and progression of various cancers." (PMID 39624057, 2024). "While YAP1 phosphorylation at Ser397 is frequently associated with its targeting for cytoplasmic retention and proteasomal degradation in a Hippo-dependent manner, its role in the context of cancer remains ambiguous." (PMID 38467828, 2024). "YAP1 is a downstream effector of the hippo signaling pathway and associated with cancer." (PMID 38967794, 2024). "Yes-associated protein 1 (YAP1) has been shown to have an oncogenic role in several cancers." (PMID 38201661, 2024). "Human cancers frequently display hyperactivation of the Hippo signaling pathway and its downstream transcriptional coactivators Yes-associated protein 1 (YAP1) and Transcriptional activator with PDZ-binding motif (TAZ), in response to a variety of stimuli, including mechanical cues." (PMID 37215087, 2023). "Thus, when FAT4 is inactivated through acquired mutations, inhibition of YAP1 cell proliferation is reduced and YAP1 signaling enhances the growth and invasion of cancer cells." (PMID 37072406, 2023). "Therefore, YAP1 tyrosine phosphorylation represents a potential mechanism for SRC activation-associated human cancers." (PMID 36633714, 2023). "Point mutations in YAP1 or TAZ are relatively rare in most cancer types." (PMID 38067201, 2023). "In addition to serving as a co-factor for TEAD transcription factors in regulating Hippo signaling, YAP1 is also an important regulator of the Wnt/β-catenin pathway, whose dysregulation has been critically linked to cancer progression." (PMID 37537569, 2023). "In addition, SRC-dependent YAP1 activation has been demonstrated to be critical for the establishment and maintenance of cancer-associated fibroblasts." (PMID 36633714, 2023). "Interestingly, FAT1 loss-of-function mutations are frequent in cancer and result in YAP1 activation." (PMID 36635265, 2023). "YAP1 also contributes to the survival of cancer cells by inhibiting apoptosis-associated genes." (PMID 35407556, 2022). "YAP1 inhibition by small-molecule inactivation of YAP1 or associated proteins has become an increasingly promising therapeutic strategy to treat aggressive cancers." (PMID 35356283, 2022). "Whether YAP1 activity in cancer-associated fibroblasts drives the production of CSF1 or other growth factors is an important open question." (PMID 35930670, 2022). "Furthermore, cancer-promoting effect caused via silencing miR-149-5p was partly saved by YAP1 downregulation." (PMID 35864972, 2022). "Mechanistic studies showed that treatment of fibroblasts with viral product-containing exosomes promoted the characteristics of cancer-associated fibroblasts by stimulating YAP1 signaling and the production of the immunosuppressive cytokines IL8, CCL2, and IL6." (PMID 35986369, 2022). "High expression of YAP1 is associated with poor survival outcomes in certain cancer types." (PMID 36479120, 2022). "In this study, high expression of YAP1 was associated with TGF-β signaling in pan-cancer." (PMID 36479120, 2022).